IL13RA2 (interleukin 13 receptor subunit alpha 2)
Diseases named in the same sentence as IL13RA2 in open-access papers (continued):
Sharing a sentence is not in itself a finding about the gene and the disease.
brain tumors (continued). "In expectation that the similarities between human and canine primary brain tumors exist at the genetic/molecular level, we preliminarily screened 40 canine archival tumor specimens for IL-13RA2 gene expression." (PMID 24147065, 2013). "IL-13RA2 is an attractive molecular target in a variety of human malignancies and in primary brain tumors in particular." (PMID 24147065, 2013). "We have generated reagents for both detection and therapeutic targeting of IL-13RA2 in human and canine brain tumors." (PMID 24147065, 2013). "In addition, we observed a strong correlation of the SHN3 prognostic value with MMP9 and IL13Rα2 in highly aggressive brain tumors, thyroid and renal cancer, which supports a close functional association with these proteins." (PMID 37963919, 2023). "The availability of specific and sensitive antibodies recognizing the receptor under various conditions will be important in further studies examining the pathophysiological role of IL-13RA2 in brain tumors, including its closest translational model in a form of spontaneous canine tumors." (PMID 24147065, 2013). "To verify the exact expression profile of IL13RA2 in various primary brain tumors, and validate the canine translational model we generated bi-species specific antibodies against IL-13RA2 against three different regions of the receptor with 100% sequence identity." (PMID 24147065, 2013). "As a trivalent vaccine targeting EphA2, HER2, and IL-13Rα2 in pediatric malignant gliomas and ependymomas revealed feasibility, tolerability, and efficacy pediatric brain tumors, combination of targeted antigens might be the future direction of the development of CAR T-cell therapy." (PMID 33673696, 2021). "In a previous clinical trial of i.c.v. infused IL13Rα2-targeted CAR T cells and i.v. infused Her2-specific CAR-modified virus-specific T cells (VSTs), efficacy of CAR T cells to multifocal brain tumors was observed." (PMID 34819930, 2021). "In addition to GBM, other brain tumors, such as high grade oligodendrogliomas, meningiomas and canine choroid plexus papillomas, appear to express the receptor at high levels and thus may be appropriate candidates for IL-13RA2-targeted imaging/therapies." (PMID 24147065, 2013). "Increased IL13RA2 mRNA expression was found in pediatric-type diffuse high-grade gliomas (pHGG) compared to non-neoplastic brain tissue and other pediatric brain tumors." (PMID 39711568, 2024). "IL-13RA2 is a cell surface receptor that is not significantly expressed in normal brain tissue; however, it is overexpressed in most cancer cells and is currently important in the treatment of brain tumors." (PMID 37867596, 2023). "In addition, knocking-out epigenetic modifier DNMT3A improved IL13Ra2-CAR T cell effector functions in preclinical brain tumor models while antigen negative relapsed have been observed." (PMID 34760690, 2021). "Yet, despite defining several potentially effective targets in adult brain tumors (e.g., IL13Rα2, HER2, and EGFRvIII), clinical testing of CAR T cells in brain tumors failed to produce complete and sustainable antitumor responses." (PMID 34760690, 2021).
pancreatic cancer (25 papers, 2011 to 2025). "We evaluated the expression of IL-13Rα2 in surgically resected pancreatic cancer and determined any association with post-operative patient prognosis." (PMID 34201539, 2021). "We analyzed the association of IL-13Rα2 expression with perineural invasion of the pancreatic cancer." (PMID 32443847, 2020). "A recent pathway-based analysis of pooled GWAS data reported that T-helper (Th) immune response genes (Th1/Th2), such as transforming growth factor-beta receptor 2 (TGFBR2), chemokine ligand 18 (CCL18), and IL13RA2, were associated with pancreatic cancer risk." (PMID 25945796, 2015). "We demonstrate for the first time that IL-13Rα2, a tumor antigen, is highly susceptible to epigenetic modulation in pancreatic cancer cell lines." (PMID 21477288, 2011). "We have previously demonstrated that IL-13-PE is a powerful anti-cancer agent, causing regression of IL-13Rα2-positive human tumors derived from variety of human cancers including pancreatic cancer." (PMID 21477288, 2011). "One study demonstrated that overexpression of IL13RA2 impaired tumor growth in murine models of breast and pancreatic cancer." (PMID 40663259, 2025). "Further, overexpression of IL13RA2 inhibits breast and pancreatic tumor growth in vivo, and silencing of the receptor promotes proliferation, survival, and migration in hepatocellular carcinoma." (PMID 40663259, 2025). "We have shown recently that Pep-1-Phor21 kills pancreatic cancer cells by targeting IL-13Rα2 since the cells lost sensitivity to this hybrid peptide when the receptor expression was downregulated in these cells by using its siRNA." (PMID 37345109, 2023). "The histone deacetylase inhibitor and DNA methyltransferase inhibitors have been shown to upregulate IL-13Rα2 expression in pancreatic cancer." (PMID 36830725, 2023). "In an orthotopic pancreatic cancer mouse model, the IL-13Rα2-positive tumor was highly invasive to surrounding organs and cause metastases." (PMID 34201539, 2021). "We demonstrated that IL-13Rα2 promoted pancreatic cancer metastasis by activating matrix metalloproteinases (MMPs) transcription, and its effect was reversed by the knockdown of IL-13Rα2 expression." (PMID 34201539, 2021). "Several studies have shown the excessive existence of the IL-13Rα1 and IL-13Rα2 chains in pancreatic cancer." (PMID 33804263, 2021). "The results of our study using resected pancreatic cancer specimens suggest a relationship between IL-13Rα2 expression and perineural invasion." (PMID 34201539, 2021). "In addition, it has also been detected that higher levels of IL-13Rα2 were expressed in lymph node metastasis and areas of perineural invasion, which indicates that IL-13Rα2 may be associated with invasion and metastasis in pancreatic cancer." (PMID 33804263, 2021). "We have reported that IL-13Rα2 is a prognostic biomarker for malignant glioma, adrenocortical cancer, and pancreatic cancer." (PMID 34201539, 2021). "We have investigated the mechanisms of cancer invasion and metastasis as well as the involvement of the IL-13/IL-13Rα2 axis in pancreatic cancer." (PMID 34201539, 2021). "IL-13Rα2 is highly expressed in various cancers, including pancreatic cancer, and consists of three domains: extracellular, transmembrane, and cytoplasmic." (PMID 34201539, 2021). "In pancreatic cancer, we have demonstrated that approximately 50% of primary and established cell lines express high levels of IL-13Rα2, and more than 70% of clinical specimens express high levels as well." (PMID 34201539, 2021). "Conversely, the knock-in of IL-13Rα2 to IL-13Rα2-negative pancreatic cancer cells increased tumor invasion and metastasis." (PMID 34201539, 2021). "Anti-tumor abilities of IL-13 cytotoxins have been shown in vivo, particularly in IL-13Rα2-positive pancreatic cancer cell lines, and also in animal models of human pancreatic cancer." (PMID 33804263, 2021).
pancreatic cancer (continued). "It was reported that IL13Rα2 was a functional receptor-mediating-signaling pathway in human pancreatic cancer cell lines." (PMID 33917914, 2021). "In pancreatic cancer, IL-13 can signal after binding to IL-13Rα2 via the AP-1 pathway, and IL-13Rα2 expression is dependent upon histone acetylation." (PMID 32443847, 2020). "We have previously reported that approximately 70% of pancreatic cancers express moderate to high-density IL-13Rα2." (PMID 32443847, 2020). "IL13ra2 (Interleukin-13 receptor α2 chain) has also been shown to inhibit tumorigenicity of breast and pancreatic cancer in animal models." (PMID 31534547, 2019). "We have previously reported that IL-13Rα2 is a functional receptor as IL-13 mediates signaling in human pancreatic cancer cell lines." (PMID 30572904, 2018). "In our recent study on the role of IL-13Rα2 in pancreatic cancer invasion and metastasis, we demonstrated that IL-13Rα2–positive cancer metastasized to lymph nodes, liver, and peritoneum at a significantly higher rate compared with IL-13Rα2–negative tumors." (PMID 23421960, 2013). "The effects of TSA and SP600125 on IL-13Rα2 protein expression in pancreatic cancer cells were also analyzed by IHC." (PMID 21477288, 2011). "When pancreatic cancer lines expressing undetectable levels of IL-13Rα2 were treated with TSA, histone H3 and H4 acetylation was dramatically increased." (PMID 21477288, 2011). "Next, we evaluated anti-cancer effect of combination of SAHA and IL-13-PE in IL-13Rα2-positive pancreatic cancer model (HS766T and MIA-PaCa2)." (PMID 21477288, 2011). "As we have shown that IL-13 can upregulate Matrix metalloproteinases (MMPs) expression in IL-13Rα2 expressing pancreatic cancer cell lines, we investigated the impact of IL-13Rα2 upregulation by HDAC inhibitors by examining IL-13 induced MMPs expression." (PMID 21477288, 2011). "We have identified a novel function of histone modification in the regulation of IL-13Rα2 in pancreatic cancer cell lines in vitro and in vivo." (PMID 21477288, 2011). "We examined epigenetic regulation of IL-13Rα2 in a murine model of human pancreatic cancer by Bisulfite-PCR, sequencing for DNA methylation and chromatin immunoprecipitation for histone modification." (PMID 21477288, 2011). "We found that pancreatic cancer cell lines that highly express IL-13Rα2 (HS766T, MIAPaCa2, and KLM), and those which express undetectable levels (Panc-1 and ASPC-1), both show high c-jun activity." (PMID 21477288, 2011). "TSA also increased acetylation in pancreatic cancer cells expressing high levels of IL-13Rα2 but this increase was less dramatic." (PMID 21477288, 2011). "Consistently, IL-13Rα2 stimulated in vivo metastasis of pancreatic cancer cells in animal models." (PMID 39598436, 2024). "IL-13 may also directly promote cancer cell proliferation and metastasis through an alternative IL-13Rα2 for example in pancreatic cancer." (PMID 37455828, 2023). "IL-13Rα2 gene expression is epigenetically regulated in pancreatic cancer." (PMID 36830725, 2023). "Furthermore, gene transfer of IL-13Rα2 into tumors dramatically sensitized tumors to IL-13 cytotoxin therapy, which was also observed in pancreatic cancer." (PMID 33804263, 2021). "In conclusion, IL-13Rα2 can be a potential diagnosis and prognostic biomarker and a marker for therapeutic response to conventional as well as cutting-edge cellular and gene therapy approaches for pancreatic cancer." (PMID 34201539, 2021). "The fact that silencing of IL-13Rα2 inhibited invasion of HS766T cells in a Matrigel invasion assay points out that IL-13Rα2 may be a therapeutic target for pancreatic cancer treatment." (PMID 33804263, 2021). "In pancreatic cancer, a small sample of tissue could be examined for the expression of IL-13Rα2 by using the endoscopic ultrasound-fine needle aspiration technique (EUS-FNA)." (PMID 34201539, 2021).
pancreatic cancer (continued). "IL13Rα2 was hypothesized to be a decoy receptor for IL13Rα1 and the type II IL-4R complex, but updated evidence suggests that IL-13 may signal through IL-13Rα2 to promote pancreatic cancer cell proliferation and invasion." (PMID 33804263, 2021). "We have investigated the biological implications of IL-13Rα2 overexpression in pancreatic cancer." (PMID 34201539, 2021). "It has been demonstrated that high levels of IL-13Rα2 mRNA were expressed in SW1990, MIA-PaCa-2, KLM, HS766T, and BxPC3 pancreatic cancer cell lines, while extremely low expression of IL-13Rα2 was examined in normal pancreatic cells including fibroblasts and ductal epithelial cell lines." (PMID 33804263, 2021). "PET/CT targeting IL-13Rα2 may be useful not only for the diagnosis of pancreatic cancer but also evaluating the expression level of IL-13Rα2 and predicting the efficacy of therapy targeting IL-13Rα2." (PMID 34201539, 2021). "In IL-13Rα2-positive pancreatic cancer, the possibility of celiac plexus invasion can be predicted in advance of surgery, and it may be possible to manage the pain in the patients receiving chemotherapy." (PMID 34201539, 2021). "We have also demonstrated that IL-13 can enhance pancreatic cancer invasion and metastasis after binding to IL-13Rα2 via the upregulation of extracellular-signal-regulated kinase (ERK) and Matrix metallo-proteinases (MMPs) in the murine orthotopic pancreatic cancer model." (PMID 32443847, 2020). "Interestingly, by correlation coefficient analysis, pancreatic cancer invasion to the neuroplexus and nerve strongly correlated with IL-13Rα2 expression in tumors obtained from both hospitals." (PMID 32443847, 2020). "Pancreatic cancer also overexpresses moderate to high-density IL-13Rα2 in about 70% of the samples." (PMID 32443847, 2020). "In pancreatic cancer cell lines, histone deacetylation inhibition increases IL13RA2 expression." (PMID 31607839, 2019). "We took advantage of upregulation of IL-13Rα2 in pancreatic cancer cell lines and hypothesized that HDAC inhibitors may enhance the sensitivity of IL-13 receptor-targeted immunotoxin, IL-13-PE, in pancreatic cancers." (PMID 21477288, 2011). "In contrast, TSA caused a significant decrease in H3K9 methylation in pancreatic cancer cells with undetectable levels of IL-13Rα2 expression but no change in high IL-13Rα2 expressing cell lines." (PMID 21477288, 2011). "In the present study, we have examined the epigenetic regulation of the IL-13Rα2 gene in pancreatic cancer cell lines and investigated whether the IL-13Rα2 gene can be modulated by epigenetic mechanisms." (PMID 21477288, 2011). "Eleven pancreatic cancer cell lines and three types of normal cell lines (fibroblast, umbilical vein endothelial cells and pancreatic ductal epithelial cells) were examined for IL-13Rα2 expression." (PMID 21477288, 2011). "As the relationship between histone acetylation and IL-13Rα2 expression levels was observed, we tested whether HDAC inhibitors can modulate IL-13Rα2 expression in pancreatic cancer cell lines." (PMID 21477288, 2011). "Seventy-one percent of pancreatic tumors overexpressed IL-13Rα2 chain." (PMID 21477288, 2011). "The role of IL‐13Rα2 in tumorigenesis is debatable as high levels of IL‐13Rα2 were found to inhibit the progression of breast and pancreatic tumors; conversely, IL‐13Rα2 overexpression was found to increase the invasiveness and metastatic potential of ovarian and pancreatic cancer cells." (PMID 34758182, 2022). "A similar technique could be utilized for the diagnosis of pancreatic cancer expressing IL-13Rα2." (PMID 34201539, 2021). "Though we did not investigate the presence of metastasis in this model, the pancreatic tumor cells collected from lymph nodes metastasis were much more sensitive to IL-13-PE in vitro than compared with primary tumor cells indicating higher level of IL-13Rα2 in metastatic lesion." (PMID 23421960, 2013).
pancreatic cancer (continued). "Interestingly, similar to histone acetylation, TSA treatment resulted in increased IL-13Rα2 mRNA expression in pancreatic cancer cell lines that normally have undetectable levels of IL-13Rα2 expression, while no changes were seen in cells expressing high levels of IL-13Rα2 mRNA or normal cell lines." (PMID 21477288, 2011). "Our present results also show a similar trend and demonstrate that 66% of surgically resected pancreatic cancer samples obtained from NTT and YCU hospitals expressed IL-13Rα2." (PMID 32443847, 2020). "There is only one CpG site in the IL-13Rα2 promoter region, but that CpG site was not methylated in two pancreatic cancer cell lines and in the normal epithelial cells of the pancreatic duct." (PMID 34201539, 2021). "IL-13Rα2 is expressed in HS766T and MIAPaCa-2 pancreatic cancer cells, as well." (PMID 33450900, 2021). "Exogenous IL-13 was shown to induce the expression of MMPs including MMP-9, MMP-12, and MMP-14, which were related to pancreatic cancer invasion in IL-13Rα2-positive pancreatic cancer cells independent of STAT6 phosphorylation." (PMID 33804263, 2021). "Histones (H3 and H4) were highly acetylated at the promoter region of IL-13Rα2 in IL-13Rα2-positive pancreatic cancer cell lines, but not in IL-13Rα2-negative cell lines." (PMID 21477288, 2011). "IL-13Rα2-negative pancreatic cancer cell lines (Panc-1 and ASPC-1) were implanted in the flanks of immunodeficient mice and treated with two different HDAC inhibitors, TSA and SAHA followed by IL-13-PE immunotoxin." (PMID 21477288, 2011). "On the other hand, histones at IL-13Rα2 promoter region were highly-acetylated in IL-13Rα2-positive but much less in receptor-negative pancreatic cancer cell lines." (PMID 21477288, 2011). "We examined the stability of upregulated IL-13Rα2 expression in IL-13Rα2-expressing and negative pancreatic cancer cell lines when treated with HDAC inhibitor." (PMID 21477288, 2011). "Epithelial cells exhibit a similar histone modification pattern to IL-13Rα2-negative pancreatic cancer cell lines but, IL-13Rα2 is not upregulated in normal epithelial cells by HDAC inhibitors." (PMID 21477288, 2011). "We demonstrate for the first time that three different HDAC inhibitors dramatically upregulate IL-13Rα2 in pancreatic cancer cell lines expressing no or low levels of IL-13Rα2." (PMID 21477288, 2011). "When cells were treated with HDAC inhibitors, not only histone acetylation but also IL-13Rα2 expression was dramatically enhanced in receptor-negative pancreatic cancer cells." (PMID 21477288, 2011). "We found that CpG sites in IL-13Rα2 promoter region were not methylated in all pancreatic cancer cell lines studied including IL-13Rα2-positive and IL-13Rα2-negative cell lines and normal cells." (PMID 21477288, 2011). "qRT-PCR analysis identified five pancreatic cancer cell lines (HS766T, MIAPaCa2, KLM, SW1990 and BxPC3), which expressed high levels of IL-13Rα2 mRNA, and six cell lines (Panc-1, ASPC-1, HPAF-II, Mpanc96, PK-1 and Capan-1) expressed low levels IL-13Rα2 mRNA (negative cell line)." (PMID 21477288, 2011). "More importantly, HDAC inhibitors sensitized pancreatic tumor cells to IL-13-PE and mediated enhanced sensitivity even though these cells did not naturally express IL-13Rα2." (PMID 21477288, 2011). "Interestingly, when cells were treated with histone deacetylase (HDAC) inhibitors, not only histone acetylation but also IL-13Rα2 expression was dramatically enhanced in IL-13-receptor negative pancreatic cancer cells." (PMID 34201539, 2021). "This may be because normal cell lines show no c-jun activity, while IL-13Rα2-negative pancreatic cancer cell lines show a 2-6 fold increase in c-jun activity indicating that TSA induction of high levels of IL-13Rα2 is dependent on the AP-1/c-jun pathway." (PMID 21477288, 2011). "Similarly, as expected, IL-13 did not induce MMPs expression in IL-13Rα2-negative pancreatic cancer cell lines." (PMID 21477288, 2011).
pancreatic cancer (continued). "It is important to note that while HDAC inhibition enhanced the remarkable anti-cancer effects of IL-13-PE in pancreatic cancer models in vivo by upregulating IL-13Rα2 in the tumors, no significant upregulation of IL-13Rα2 expression was observed in any vital organs." (PMID 21477288, 2011). "As expected, IL-13 induced STAT6 phosphorylation in IL-13Rα2-negative pancreatic cancer cell lines." (PMID 21477288, 2011). "We used two human pancreatic cancer cell lines: HPAF-II, which is IL-13Rα2-negative, and HS766T, which is IL-13Rα2-positve." (PMID 34201539, 2021). "As HDAC inhibition increased IL-13Rα2 expression in IL-13Rα2-negative but not in normal cell lines, we examined whether HDAC inhibition enhanced the anti-cancer effect of IL-13-PE in IL-13Rα2-negative pancreatic cancer cell lines." (PMID 21477288, 2011).